PIK3CA (phosphatidylinositol-4,5-bisphosphate 3-kinase catalytic subunit alpha)
Diseases named in the same sentence as PIK3CA in open-access papers (continued):
Sharing a sentence is not in itself a finding about the gene and the disease.
tumor (continued). "Among the 43 patients with analysable plasma samples, 6 (14%) had detectable circulating PIK3CA mutations, corresponding to 6/11 patients (55%) with PIK3CA-mutated tumours and with detectable cfDNA and 0/32 non-mutated tumours." (PMID 34911971, 2021). "Our study showed that a corresponding circulating PIK3CA mutation was identified in 55% of LAIBC patients with PIK3CA-mutated tumours, while no circulating mutation was found among patients with PI3KCA wild-type tumours." (PMID 34911971, 2021). "Notably, two of the unclassifiable LGNET with high tumor content (uLGNET #1 and #2) had genetic signatures of RGNT with FGFR1 kinase domain hotspot missense mutation in combination with PIK3CA or PIK3R1 mutation." (PMID 32859279, 2020). "MiR‐152‐3p might serve as a tumor suppressor in human BC cells via negatively regulating PIK3CA expression to inhibit the activation of AKT and RPS6, leading to suppression of BC cell proliferation (Ge, Wang, Kong, Gao, & Sun, 2017)." (PMID 32124558, 2020). "The possible elimination of the sub-clone harboring mutations in mTOR, PIK3CA and a FAT4 due to adjuvant chemotherapy could have happened either in the primary tumor or in the metastasis." (PMID 31953485, 2020). "Of note, N345K mutation in exon 4, which represents 6% of all tumor samples with a PIK3CA mutation, is not part of the therascreen panel." (PMID 32404150, 2020). "Although PIK3CA mutations are relatively common in cancers, especially in NSCLC, whether they play a role in the tumor development and prognosis of NSCLC patients indeed remains controversial up to now." (PMID 32908885, 2020). "With the caveat of low patient numbers, in PIKTAM PIK3CA mutation detection in ctDNA did not seem to add predictive power as compared to tumor tissue‐based biomarker detection." (PMID 32352244, 2020). "Recently, SOLAR-1 study demonstrated that the combination of alpelisib and fulvestrant, a selective estrogen receptor degrader, prolonged progression-free survival among patients with PIK3CA-mutated, hormone receptor-positive, HER2-negative advanced breast cancer." (PMID 32704014, 2020). "Importantly, the combination of PI3K and CDK 4/6 inhibitors overcome intrinsic and adaptive resistance to PI3K inhibitors leading to tumor regression in PIK3CA mutant xenografts." (PMID 32899866, 2020). "Genomic testing confirmed that the tumor was of basal-like intrinsic subtype, without evidence of an activating PIK3CA mutation." (PMID 33138866, 2020). "Her tumor also expressed an amplification of PIK3CA, which may serve as a therapeutic target in the future." (PMID 32411090, 2020). "PIK3CA mutations in BC are heterogenous and ~ 20% of patients with a known PIK3CA mutation, and 95% with a known double PIK3CAmut tumor, would not be captured by the therascreen panel." (PMID 32404150, 2020). "Moreover, the curve of p.E545K PIK3CA in EFIRM showed similarity to those of tumor volume (R = 0.70, P = 0.00) and p.E545K PIK3CA in NGS (R = 0.72, P = 0.00)." (PMID 32793495, 2020).
tumor (continued). "When testing for PIK3CA mutations in ABC, various factors should be considered by pathologists and oncologists, including choice of assay, sample availability, sample collection and preparation, time of screening, and tumor heterogeneity and evolution." (PMID 32697890, 2020). "A previous study reports that blood-derived circulating tumor DNA markers, such as PIK3CA with frequent alteration, may be key biomarkers in diagnosis of advanced HCC and for HCC molecular diagnosis." (PMID 33072579, 2020). "In tumors with mutations of KRAS, NRAS, PIK3CA, or BRAF, the proportion of VAF with different mutations in tumor cell samples of the same patient varies significantly, which may also reflect the ITH of tumor cells." (PMID 32853464, 2020). "While tumor xenografts generated by the injection of CSC#2 and 7 were sensitive to the combined treatment of BMP7v and chemotherapy, PIK3CA-mutant tumor xenografts derived from the implantation of CSC#1 delayed the outgrowth showing a kinetic trend similar to that of tumors treated with vehicle." (PMID 31591478, 2020). "These are also involved e.g. in AKT regulation (PIK3CA) and tumor suppression (PTEN)." (PMID 31758407, 2020). "In the six patients with tumor alterations in PIK3CA, AKT1, or PTEN, the best overall response was SD < 4 months (n = 3, including the two patients with AKT1-altered tumors and one patient with PTEN K237fs mutation), progressive disease (n = 2), and non-evaluable (n = 1)." (PMID 33138866, 2020). "The presence of PIK3CA mutations at allelic fractions of less than 50% suggests that PIK3CA mutations are not present in all or most tumor cells." (PMID 32537547, 2020). "In July 2014, the primary tumor was biopsied and the first plasma sample was taken, showing no pathogenic or likely pathogenic variants in the PIK3CA or ESR1 gene." (PMID 31254045, 2020). "There was a strong, positive association between PIK3CA and PTEN mutations in the BSA, but not BW, group in which 78% (7/9) of PIK3CA-mutant tumours were also carrying a PTEN mutation versus only 11% (2/18) for wt-PIK3CA tumours (p = 0.0012)." (PMID 32520976, 2020). "Analysis of ctDNA or tumor mRNA from patients enrolled in the PALOMA-3, NeoPalAna and MONALEESA-3 trials have identified Rb mutations, activating mutations in PIK3CA and ESR1, increased cyclin E1 and activation of the PDK1-AKT axis as some of the drivers of resistance." (PMID 32344635, 2020). "Mutations with high VAFs indicated early appearance during tumorigenesis or tremendous contribution to later expansion of tumor cells, and the previous study demonstrated AKT1, CBFB, MAP2K4, ARID1A, FOXA1, and PIK3CA mutations have relatively high average VAFs in breast cancers." (PMID 33173047, 2020). "Together with alpelisib, the FDA also approved the companion diagnostic therascreen® PIK3CA test (QIAGEN Manchester, Ltd.)used in SOLAR-1 to select patients who had PIK3CA mutations in tumor tissue specimens and/or in circulating tumor DNA (ctDNA) isolated from plasma specimens." (PMID 32404150, 2020). "Next, we explored the effect of PIK3CA knockdown on tumor growth and metastasis in vivo." (PMID 33344221, 2020). "Sequencing results were obtained for nine tumor samples; no mutations of PIK3CA or PTEN were detected." (PMID 30446785, 2019).
tumor (continued). "Similarly, we showed that the PTEN/ARID4B/PIK3CA signature has greater predictive power for tumor recurrence than any individual gene alone or two genes combined." (PMID 31551414, 2019). "Furthermore, tumour growth decreased in the mutant PIK3CA–PDX model following administration of GSK112012 (3 mg/kg) and NVP-TNKS656 (50 mg/kg), the latter of which targets the WNT pathway." (PMID 30944457, 2019). "Furthermore, neratinib significantly inhibited tumor growth in a HER2-positive, PIK3CA-mutated patient-derived xenograft BC model." (PMID 30867034, 2019). "Bioinformatic analysis of human tumours may also allow the correlation of the timing of PIK3CA activation with CIN in whole tissues." (PMID 31374965, 2019). "Moreover, the combination of CB-839 and 5-FU induced tumor regression in three different PIK3CA mutant CRC xenograft models." (PMID 31844152, 2019). "The present correlative study attempted to further refine the HER2-positive patient population that may benefit based on PIK3CA alterations within their primary tumor." (PMID 30867034, 2019). "PIK3CA may play a significant role in tumor cell proliferation, invasion, metastasis, apoptosis or cell cycle among different cancer types." (PMID 31472672, 2019). "Patients harbouring PIK3CA mutated tumours benefit from exposure to aspirin, whereas PIK3CA wild-type patients do not." (PMID 31164962, 2019). "Pik3ca in implanted KPC cells promotes tumor progression and lethality." (PMID 31112530, 2019). "Using correlation of the expression of each tumor to the luminal A and luminal B PAM50 centroids, we found a strong correlation of tumors with both MAP3K1 (mutations/deletions) and PIK3CA mutations with a luminal A-like expression pattern vs. a luminal B expression (p < 0.0001)." (PMID 31552290, 2019). "Indeed, patients progressing on palbociclib exhibited a relative high frequency of PIK3CA and ESR1 mutations in plasma tumor ctDNA." (PMID 30914635, 2019). "Nevertheless, current studies have not investigated what effects PIK3CA had on tumor associated neutrophils (TANss)." (PMID 31472672, 2019). "Our findings suggest that PIK3CA expression may play an important role in tumor immune microenvironment and could alter fraction of TANs in UCEC." (PMID 31472672, 2019). "There were 6 tumors with coexisting mutations of the same gene (1 with 2 BRAF, 2 with 2 NRAS, 1 with 2 PIK3CA, 1 with 2 KIT, and 1 with 3 KIT mutations), and 26 tumors with coexisting mutations of different genes, including a tumor with 2 NRAS and one PIK3CA mutation." (PMID 31277584, 2019). "The tumor also contained two oncogenic missense mutations in EGFR A289V and PIK3CA G118D." (PMID 31258848, 2019). "We identified both known and novel somatic copy number aberrations (12p, MDM2, and RHBDD1) and mutations (XRCC2, PIK3CA, RITA1) including candidate markers for platinum resistance that were present in a primary tumor of mixed histology and that remained after tandem autologous stem cell transplant." (PMID 30870501, 2019).
tumor (continued). "PIK3CA/AKT/mTOR pathway gene TSC1 (Tuberous Sclerosis 1), a known cancer driver gene in HCC21 was recurrently altered via missense mutation in one ASL and one HCC tumor in this cohort." (PMID 31796844, 2019). "Because the median survival of mice with αKO/CD80KO+shB2m tumors (87.5 days) was much longer than that of mice with WT KPC tumors (16 days), we suspect that additional Pik3ca-regulated immune modulators, perhaps including cytokines, contribute to tumor immunogenicity." (PMID 31112530, 2019). "Circulating tumor DNA sequencing was performed on 195 patients enrolled in the PALOMA-3 study, comparing baseline and end-of-treatment analyses, demonstrating the emergence of driver mutations in PIK3CA and ESR1." (PMID 31396487, 2019). "However, an interesting reported finding was that patients with cystectomy and positive for PIK3CA and FGFR3 circulating mutations had a higher incidence of tumor recurrence." (PMID 31615102, 2019). "In addition, amplification of PIK3CA and FGFR2 in T2 and T3, combined with activating mutations in KRAS and PIK3CA in T1−3, indicates a critical role for the RAS-PI3K axis in tumor survival through multiple rounds of radiotherapy." (PMID 30220971, 2018). "First, we addressed the question if the inhibited tumor cell proliferation observed after KRAS-esiRNA-treatment of human CRC xenografts is also the cause for decreased tumor growth in cetuximab-antibody-coupled PIK3CA-esiRNA (C-PIK3CA-esiRNA) treatment." (PMID 30001368, 2018). "The focal gain in 3q observed in 18 of 20 (90%) tumours affects the PIK3CA gene." (PMID 29416628, 2018). "Key oncogenic kinase drug targets include the PIK3CA, BRAF, and epidermal growth factor receptor (EGFR), which activates significant tumor cell signaling pathways and is related to the mutations and/or deletions in phosphatase and tensin homolog (PTEN), a phosphatase that negatively regulates PI3K." (PMID 29455673, 2018). "Instead, PIK3CA mutations were identified in the setting of advanced extraneural relapsing disease, suggesting a potential role in MB progression rather than in tumor initiation, as suggested by preclinical models." (PMID 29515801, 2018). "Interestingly, several studies revealed a key effect of oncogenic PIK3CA on mammary cell fate, which activates a multipotent genetic program at the early stage of tumor initiation and controls tumor heterogeneity." (PMID 29942710, 2018). "Indeed, the relationship between PIK3CA mutation and p-AKT expression has been different among tumor types." (PMID 30115035, 2018). "Moreover, the prognostic value of PIK3CA was also validated in another cohort, which indicated poor prognosis of the patients with PIK3CA mutant tumor." (PMID 29970892, 2018). "In our experimental setup, PIK3CA inhibition by RNAi led to decreased tumor growth independent of the PIK3CA mutational status of the cell line: both PIK3CA wild type and mutant cell lines reacted upon treatment with PIK3CA esiRNA." (PMID 30001368, 2018). "The classical biological parameters: age, SBR histological grade, lymph node status, macroscopic tumor size, and PIK3CA mutation status, were not prognostic markers in this series of triple negative breast tumors (data not shown)." (PMID 29484124, 2018).
tumor (continued). "Besides, a statistically significant difference in PFS was found across the two arms in postmenopausal women with PIK3CA-mutant ctDNA tumor (HR = 0.52, 95% CI: 0.39–0.69)." (PMID 30235292, 2018). "The established cancer gene PIK3CA is affected in all tumor steps of two of the studied patients." (PMID 29293529, 2018). "Main concern could be represented by the status of PIK3CA, which could accelerate tumor progression, alter intrinsic phenotype of HER2+ cancers, and cause resistance to anti-HER2 therapies." (PMID 29700387, 2018). "Moreover, they show that tumor aggressive behavior is strictly dependent on the identity of the CO: expression of mutant PIK3CA in basal cells mainly give rise to benign tumors, whereas its expression in luminal cells mostly coincides with aggressive tumors." (PMID 29853913, 2018). "All the tumor areas sampled were analyzed for KRAS, BRAF, PIK3CA, and NRAS mutations." (PMID 29774112, 2018). "Of note, the tumor tissue of 2 patients achieving pCR was not available for PIK3CA mutational analysis." (PMID 29937992, 2018). "The precise mechanism by which PIK3CA and SMO mutations interplayed to promote tumor progression in our patient is unknown." (PMID 29515801, 2018). "The most frequently mutated genes across all tumor types included KRAS (30 patients), PIK3CA (16 patients), BRAF (6 patients), EGFR (5 patients), NRAS (4 patients) and ERBB2 (3 patients) whereas CCND1, ERBB2, EGFR and MYC were the genes most frequently subjected to copy number gain." (PMID 29854313, 2018). "However, a combination of C-KRAS/PIK3CA-esiRNA lead to significantly smaller tumor size in HT29 compared to control groups." (PMID 30001368, 2018). "Tumor genotyping is become standard practice for CLM and clinicians often have information on the mutational status of oncogenes, including the KRAS, BRAF, PIK3CA, and NRAS oncogenes." (PMID 29774112, 2018). "No patients with PIK3CA wild‐type tumor biopsies (n = 5) exhibited PIK3CA mutations in their corresponding serum samples." (PMID 29689598, 2018). "PIK3CA gene mutation did not correlate with overall survival (HR = 1.05, 95% CI 0.83–1.34, p= 0.666) but was significantly associated with poor tumor differentiation (OR = 0.37, 95% CI 0.17–0.76, p= 0.011)." (PMID 29484141, 2018). "Dual EGFR and MEK and/or mTOR inhibitors showed improved response in tumor models harboring aberrant biomarkers, such as RAS, BRAF and PIK3CA mutations, suggesting that they might prevent the activation of resistance pathways." (PMID 28002810, 2017). "The tumor was also tested for mutations in exons 2, 3, and 4 of the KRAS and NRAS genes, codon 600 of the BRAF gene, and exons 10 and 21 of the PIK3CA gene, and showed a mutation in PIK3CA exon 10, namely the c.1624G>A, p.Glu542Lys (previously reported by our group 15)." (PMID 29072370, 2017). "For example, cell lines with PTEN loss or PIK3CA mutations have been shown to be significantly more sensitive to the Akt inhibitors in a variety of tumor types, while cells lines with RAS mutations are generally resistant even in the presence of concomitant PIK3CA mutations." (PMID 28582410, 2017).